TNF (tumor necrosis factor)
Diseases named in the same sentence as TNF in open-access papers (continued):
Sharing a sentence is not in itself a finding about the gene and the disease.
melanoma (continued). "Human recombinant interferon beta (hrIFN-β) treatment had a strong inhibitory effect on MEL928 melanoma cell growth compared to treatments with hrIFN-γ and TNFα." (PMID 37503349, 2023). "The time frame and the junctional route of melanoma cell intercalation occurred in unstimulated, and TNF-α-stimulated pMBMECs." (PMID 37894438, 2023). "This approach identified melanoma-derived TNF-α as the major factor driving LC migration once tumors had reached a critical mass." (PMID 37043573, 2023). "al, PD-1 blockade increased the production of TNFα by these ILC2s, directly mediating B16 melanoma tumor cell death." (PMID 37514187, 2023). "For example, despite the early use of corticosteroids and anti-TNF-a treatment, 1% of melanoma patients receiving ipilimumab still have intestinal perforation." (PMID 37304306, 2023). "From 60 min after the start of the experiment, significantly more melanoma cells intercalated into IL-1β-stimulated pMBMECs than into TNF-α stimulated pMBMECs." (PMID 37894438, 2023). "Exosomal TNF-α derived from natural killer (NK) cells has also been shown to exert cytotoxic effects on melanoma cells by blocking the cell proliferation signaling pathway." (PMID 37670933, 2023). "In contrast, the two extracts decreased IL-10 levels in the B16-F10 murine melanoma model, but only P2Et treatment increased TNFα and IFNγ levels, indicating increased activation of the effector immune response." (PMID 38069022, 2023). "Induces anti-cancerous effect by activating dendritic cells, antigen-specific T cells in the C57BL/6 rodents, and releases pro-inflammatory cytokines such as TNF-α, IL-12 and IL-6 in B16 melanoma cells." (PMID 37215217, 2023). "Data obtained in human settings are in line with those from murine models, showing the reduced secretion of IFN-γ and the enhanced production of TNFα by ILC1s when they were co-cultured with melanoma cells." (PMID 36765891, 2023). "The model predicts that melanomas fail to activate LC migration to lymph nodes until tumors reach a critical size, which is determined by a positive TNF-α feedback loop within melanomas, in line with our observations of murine tumors." (PMID 37043573, 2023). "With this in mind, we added the mechanisms of TNF-α production to the melanoma model and integrated it with the LC model to create a melanoma-LC model." (PMID 37043573, 2023). "Mechanistically, we predicted that a model of melanoma-LC interaction based on TNF-α production by melanoma cells exhibited bistability in MITFhigh backgrounds." (PMID 37043573, 2023). "Conversely, another study demonstrated that systemic TNF-α blockade can both reduce the toxicities of and improve the response to immunotherapy in melanoma, suggesting that tumor response to TNF-α is tumor intrinsic and/or context dependent." (PMID 37092550, 2023). "We determined that the percentage of melanoma cell intercalation into IL-1β-stimulated pMBMECs was still significantly increased compared to TNF-α-stimulated pMBMECs." (PMID 37894438, 2023). "We profiled the IL-12 virotherapy-induced immune equilibrium in murine melanoma, identifying blockade of innate inflammatory cytokines, tumor necrosis factor alpha (TNFα), IL-1β, or IL-6 as possible synergistic interventions." (PMID 37461742, 2023). "Nevertheless, it was also reported that blockage of TNF overcome the resistance to anti-PD-1 treatment in experimental melanoma, and the treatment with TNF inhibitors enhanced the anti-tumor effect of combined CTLA-4 and PD-1 immunotherapy." (PMID 36865537, 2023). "By combining the LC and melanoma models, we developed a melanoma-LC executable model based on the impact of melanoma-derived TNF-α on epidermal LCs." (PMID 37043573, 2023). "The induction of senescence by IFN-γ and TNF-α has been described in several cancer forms such as breast cancer, rhabdomyosarcoma, and primary melanoma or sarcoma." (PMID 37610672, 2023).
melanoma (continued). "Taken together, we here demonstrate increased shear-resistant arrest of melanoma cells IL-1β-stimulated pMBMECs compared to the TNF-α stimulated pMBMECs." (PMID 37894438, 2023). "A recent phase Ib trial of nivolumab and ipilimumab in combination with TNF-α inhibitors in patients with advanced melanoma found the combination to be safe with promising clinical responses." (PMID 37813923, 2023). "In a comparable research primarily involving patients treated with TNF-α inhibitors, the IRs of melanoma and NMSC were 6.1 and 124.5 per 10,000 PY, respectively." (PMID 38276003, 2023). "Although TNF-α shows potent antitumor activity in various animal cancer models, due to its toxicity, clinical use of TNF-α is now limited to isolated limb perfusion (ILP) for melanoma and soft tissue sarcoma." (PMID 37112810, 2023). "C. acnes promoted apoptosis, enhanced fecal porphyrin secretion, upregulated TNFα, and promoted the death of residual melanoma cells after radiotherapy." (PMID 36860568, 2023). "In a subcutaneous transplant model of melanoma and lung cancer, knocking out the gene encoding TNF receptor 2, the site of action of TNFα, enhanced apoptosis and suppressed tumor growth." (PMID 36996146, 2023). "In line with a recent study indicating that besides playing a role in the immune response, HLA class I antigens are crucial to sustain glycolysis in melanoma cells, TNFα was shown to induce glycolysis in ReN-derived astrocytes." (PMID 36223047, 2023). "For example, α-pinene inhibits the production of pro-inflammatory cytokines, such as TNF-α (Tumor Necrosis Factor α) and IL-6 (Interleukin 6), in melanoma cells." (PMID 37515699, 2023). "Tumor MDM2 gene expression appears to correlate with clinical response and local disease-free survival in patients undergoing limb ILP with TNF and melphalan for in-transit melanoma metastases." (PMID 38138884, 2023). "M1-type macrophages are involved in the tumor immune process of melanoma by secreting cytokines, such as IL-1β, TNF-α, IL-12 and IL-18." (PMID 37762054, 2023). "has reported that host Gpr68-deficiency led to increased effector CD8+ T cell number and enhanced T cell proliferation, migration as well as IFNγ, TNFα and GramB production, which is responsible for the impaired melanoma tumor growth in male mice." (PMID 37350933, 2023). "All MAPK inhibitors enhance LC residency because the MAPK pathway is required for Ets-1 activity and, consequently, for TNF expression in melanoma in the model." (PMID 37043573, 2023). "The shear-resistant arrest of B78chOVA melanoma cells to IL-1β-stimulated pMBMECs was significantly enhanced compared to TNF-α-stimulated pMBMECs." (PMID 37894438, 2023). "The executable model of melanoma-LC interactions predicted that melanoma cells occupying transcriptional states with high TNF-α expression induced LC migration from the melanoma-adjacent epidermis." (PMID 37043573, 2023). "Previous studies have reported that in vivo treatment with zymosan upregulates the expression of proinflammatory cytokines such as TNFα in peritoneal macrophages, ultimately inhibiting melanoma progression." (PMID 37570749, 2023). "In parallel, overexpression of SIRT7 in WM35 melanoma cell promoted the mRNA levels and secretion of TNFα, IL-8, and VEGFα under ER stress." (PMID 36918544, 2023). "were the first to discover TNF-α in NK cell-derived EVs and confirmed the relevance of TNF-α to the cytotoxicity mediated by NKEVs in melanoma cells." (PMID 38239346, 2023). "Previous studies have predominantly focused on the risk of melanoma and NMSC in patients treated with TNF-α inhibitors." (PMID 38276003, 2023). "There is limited research into the mechanisms of TNF-α production in melanoma cells by stromal cells, and measurements in cell culture have found variability in TNF-α production between cell lines." (PMID 37043573, 2023).
melanoma (continued). "Intriguingly, human NK cells degranulated less and showed reduced synthesis of TNFα after cocultivation with NGFR-overexpressing melanoma cells compared to control cells." (PMID 36638181, 2023). "The number of TNF-α expressing tumor-infiltrating T cells was markedly reduced in melanoma-bearing mice." (PMID 36726985, 2022). "After intra-tumoral injection with C. acnes, the growth of melanoma cells was inhibited through the induction of Th1 type cytokines such as IL-12, tumor necrosis factor alpha (TNF-α), and interferon gamma (IFN-γ)." (PMID 35163734, 2022). "This privation of effector function involves the loss of TNF-α, IFN-γ and high levels of PD-1, as reported in several human cancers such as melanoma, NSCLC, HNSCC, gastric cancer and ovarian cancer." (PMID 35406451, 2022). "We found that knockout of PP6 in various cancer cell lines including B16-F10 melanoma cells reduced the sensitivity to TNFα." (PMID 36071040, 2022). "One study reported that B cells from melanoma patients' peripheral blood express TNF-α and/or IL-6, and TNF-α transcripts from single B cells extracted from melanoma metastases were associated with reduced responsiveness to checkpoint inhibitor immunotherapy." (PMID 35909944, 2022). "In the group of melanoma-CM-educated moDCs, TNFα secretion negatively correlated with the ability of moDCs to induce IL-10 producing CD4+CD25+ T cells." (PMID 36194602, 2022). "Upon lung infiltration, IVneg CD4+ and CD8+ T cells significantly upregulated TNFα expression in WT and B2m-/- B16 melanoma-challenged mice compared to the controls." (PMID 36733396, 2022). "Previously, AAVP-RGD4C was also successfully used to deliver TNF-α to the tumor vasculature in human melanoma xenografts." (PMID 36430720, 2022). "The SPION approach has also been used to enhance the cytotoxic effect of the pro-apoptotic cytokine, TNFα, in melanoma cells." (PMID 36591444, 2022). "The mRNA expression level of inflammatory cytokines such as IL-1β, IL-6, and TNF-α confirmed the macrophage activation state upon the treatment with the acid EV derived from all the three melanoma cell lines used." (PMID 36291876, 2022). "For example, TNFα/TNFR1 deficiency, as well as antibodies to TNFα, have improved the ability of anti-PD-1 antibodies to reduce tumor load and increase survival in a melanoma model." (PMID 35884574, 2022). "Subsequently, BRAF inhibition results in paracrine suppressive activity of melanoma cells on dendritic cells by inhibiting their excretion of pro-inflammatory cytokines, namely IL-12 and tumor necrosis factor alpha (TNFα)." (PMID 35565255, 2022). "PD-1 blockade on murine ILC2s in melanoma lung metastases can upregulate the production of ILC2-derived TNF-α, and TNF-α induces tumor hemorrhagic necrosis." (PMID 35720302, 2022). "Overall, these findings show that the administration of a combination of PTS and cisplatin strongly inhibited the expression of the inflammatory cytokines IL-1β, TNF-α, and IL-6 in canine melanoma." (PMID 36077992, 2022). "In the same report, we showed that co-administration TNF with 100-nm liposomes resulted in a higher drug accumulation to a murine melanoma tumor, compared to 100-nm liposomes alone (6.3-fold 12 h after administration, and 5.5-fold at 24 h)." (PMID 36297598, 2022). "IFN-γ and TNF, doxorubicin, and palbociclib treatment inhibited the growth of melanoma cells during the treatment period." (PMID 35563820, 2022). "In a recent mouse study, MAPKi were confirmed to promote melanoma inflammation via pyroptosis, exemplified by the influx of TNF-producing T cells." (PMID 35879777, 2022). "Prior studies have demonstrated that NEX contain not only FasL and perforin but also TNFα; these molecules can all trigger melanoma cell death." (PMID 36591444, 2022). "IL-7 inhibits melanoma growth by promoting the secretion of the cytokines IL-1β, IL-1α, and tumor necrosis factor-α (TNF-α) from monocytes." (PMID 36142322, 2022).
melanoma (continued). "Co-expression of IL-12 and TNF-α was designed as an antitumor in situ vaccination and showed extensive infiltration of immune cells in the murine melanoma model." (PMID 36428682, 2022). "Other studies on SNPs in melanoma genes demonstrated that various cytokines (TNF-a, IL-6, IL-10, IFN-c, and TGF-b1) are involved in melanoma progression and immune escape." (PMID 35334544, 2022). "Tc1 cells (characterised by IFN-γ, TNF-α production) are considered as the most frequent subset present in different cancers and correlating, in some cases, to favourable prognosis (melanoma, ovarian, breast, and lung cancer)." (PMID 35406451, 2022). "With the development of novel TNF administration procedures, such as high concentrations of TNF perfusion in isolated limbs of patients with melanoma or sarcoma, the therapeutic efficacy of TNF has been demonstrated in clinical trials." (PMID 35795050, 2022). "In contrast to the significant suppression of IFNγR1KO melanomas by Ruxo in B6 mice, Ruxo was unable to suppress IFNγR1KO melanoma in TNF−/− mice (actually, reversed), highlighting a crucial role of host TNF signaling in this process." (PMID 36008408, 2022). "Long-term exposure or overexpression of TNF-α leads to cellular senescence in various cell types, including fibroblasts, melanoma cells, and hematopoietic cells." (PMID 35790884, 2022). "The effectiveness of MAPK pathway inhibitors (MAPKi) used to treat patients with BRAF-mutant melanoma is limited by a range of resistance mechanisms, including soluble TNF (solTNF)-mediated NF-kB signaling." (PMID 35879777, 2022). "TNF-α secreted from macrophages induced the release of the C-X-C motif chemokine ligand 1 (CXCL1) from melanoma and lung carcinoma cells in a paracrine manner." (PMID 36552865, 2022). "This loss of cFLIPL protein is a likely candidate for the increase in caspase-8-activation and apoptosis in Usp27xL-overexpressing and TNF- or pIC-treated melanoma cells tested here." (PMID 35044632, 2022). "Functionally, melanoma patients also displayed an impaired TNFα secretion by CD117- ILCs and CD117+ ILCs." (PMID 35173725, 2022). "For instance, in a mouse melanoma model HIF-1α-/- CD8+ T cells show decreased expression of soluble factors including TNFα, IFNγ and granzyme B and tumor infiltration under hypoxia correlating with increased tumor growth." (PMID 35769460, 2022). "The pro-inflammatory cytokine TNF-α has been shown to be involved in the progression of melanoma through the inhibition of apoptosis." (PMID 36142196, 2022). "The serum concentration of TNF-α was significantly decreased in dysbiotic mice with melanoma, which led to a marked decline in the TNF-α level in tumor tissues." (PMID 36726985, 2022). "In a mouse melanoma model, the author demonstrated that TNF impairs the accumulation of CD8+ T cells in tumor-draining lymph nodes and tumors in a TNFR1-dependent manner." (PMID 36016934, 2022). "Encouraged by these data and previous reports on TNF-α blockade to improve anti-PD-1 therapy efficacy in a mouse model of melanoma and colon carcinoma, we evaluated the therapeutic potential of TNF-α and PD-L1 co-blockade in the LLC-Fluc model." (PMID 35493461, 2022). "In circulation, only IVpos CD8+ T cells from mice that received WT B16 melanoma cells significantly upregulated TNFα expression." (PMID 36733396, 2022). "The concentrations of IL-1β, TNFα, and IL-10 were assessed in the peripheral blood plasma obtained from the healthy animals (control) and animals bearing S91 melanoma tumors at different stages of growth." (PMID 35053477, 2022). "It has been shown that treatment with MAPKi leads to increased numbers of TAM in melanoma lesions, and that tumor necrosis factor (TNF) released by TAMs induces melanoma resistance to MAPKi, blocking apoptosis mediated by inhibition of BRAF signaling." (PMID 35879777, 2022). "TNF is a growth factor for melanoma that blocks MAPKi-induced apoptosis in BRAFV600E+ melanomas via NF-kB signaling." (PMID 35879777, 2022).
melanoma (continued). "In sum, these results indicate that Ruxo selectively suppresses the growth of IFNγR1KO melanoma in a T cell and TNF-dependent manner." (PMID 36008408, 2022). "TNFα expression in IVpos circulating and IVneg lung-infiltrating NK cells was significantly enhanced in the lungs of mice that received WT and B2m-/- B16 melanoma cells." (PMID 36733396, 2022). "The ability of melanoma cell lines to acquire MAPKi resistance in response to recombinant or macrophage-derived TNF was evaluated using the MTT cytotoxicity assay." (PMID 35879777, 2022). "TAMs affect melanoma cells by releasing TNF alpha, thereby sustaining survival signaling pathways in melanoma cells by enhancing MITF expression." (PMID 35558554, 2022). "TNFα exerts indirect cytotoxic effects against melanoma by inducing the destruction of tumor vasculature." (PMID 35173725, 2022). "A phase Ib trial is currently evaluating the combination of ipilimumab and nivolumab along with the anti-TNF-α antibodies certolizumab or infliximab in patients with advanced melanoma (NCT03293784)." (PMID 35743911, 2022). "The engagement of CTLA-4 on primary melanoma cell lines induces antibody-dependent cellular cytotoxicity and TNF-α production." (PMID 35493488, 2022). "TNF-α secreted by macrophages stimulated CXCL1 production in melanoma cells to facilitate tumor growth and metastasis." (PMID 36552865, 2022). "Previous studies have shown that birinapant inhibits the growth of many melanoma cell lines if combined with TNF-α treatment." (PMID 35296667, 2022). "TAMs can release arachidonic acid, tumor necrosis factor-α (TNF-α), TGF-β, and IL-6 in melanoma, causing cancer cells to produce VEGF-A, which accelerates angiogenesis." (PMID 36072596, 2022). "Among them, CD8+ T cells lose their ability to induce the death of melanoma cells leading to immune escape after exposure to melanoma-derived exosomes, manifested as reduced TNF-α secretion and damaged T-cell receptor (TCR) signaling pathway." (PMID 36612077, 2022). "Blockade of the TNF-α/TNFR-1 signaling axis led to an increase in the proportion of melanoma-specific CD8+ T-cells in the tumor and delayed tumor growth." (PMID 33920379, 2021). "To determine if ILC2 TNF-α production was taking place in our in vivo B16 melanoma models, we i.v. injected B16 melanoma to a cohort of WT and PD-1-/- mice." (PMID 34531874, 2021). "A phase 1b clinical trial (TICIMEL) is currently investigating the efficacy of infliximab or certolizumab (anti-TNFα) and immune checkpoint inhibitor combination in patients with advanced melanoma (NCT03293784)." (PMID 34073253, 2021). "In another experiment performed on mice, using in vivo injections of C. acnes in malignant melanoma (MM), Th1 cells activated by C. acnes produced the antitumor cytokines IL-12, tumor necrosis factor alpha (TNF-α), and INF-γ." (PMID 33803499, 2021). "Our study shows that TNFα potently drives a program of melanoma dedifferentiation, particularly in melanocytic and transitory melanomas." (PMID 34073253, 2021). "Melanoma cells treated with TNF-α reduced the epithelial marker E-cadherin and induced mesenchymal markers N-cadherin, vimentin, fibronectin." (PMID 33986746, 2021). "They participated in pathways concerning melanoma, such as TNF signaling pathway, pathways in cancer, FoxO signaling pathway, cell cycle, Hippo signaling pathway, and TGF-beta signaling pathway." (PMID 33897771, 2021). "The NGR–TNF showed enhanced efficacy against murine lymphoma and melanoma even at lower doses compared to the TNF." (PMID 33918106, 2021). "The influence of exogenous TNFα on melanoma dedifferentiation markers, immune inhibitory checkpoints PD-L1 and PD-L2, and antigen-presenting molecules HLA-ABC and HLA-DR was examined." (PMID 34073253, 2021). "In patients with melanoma (phase Ib), it was found that the TNF inhibitors (infliximab or certolizumab) can boost the antitumor effect of ICIs (ipilimumab and nivolumab)." (PMID 33801589, 2021).